ID4 (inhibitor of DNA binding 4)
Description:
Transcriptional regulator (lacking a basic DNA binding domain) which negatively regulates the basic helix-loop-helix (bHLH) transcription factors by forming heterodimers and inhibiting their DNA binding and transcriptional activity. Implicated in regulating a variety of cellular processes, including cellular growth, senescence, differentiation, apoptosis, angiogenesis, and neoplastic transformation (By similarity).
Synonyms: bHLHb27; IDB4
Tractability: No criterion of Open Targets' tractability assessment is met for any kind of drug.
Gene: Protein-coding gene on chromosome 6 (19,837,366 to 19,842,197, forward strand). Ensembl gene ENSG00000172201.
Subcellular location: Nucleus
Subcellular location (Human Protein Atlas): Nucleoplasm
Pathways (Reactome):
Developmental Biology: Formation of the nephric duct
Signal Transduction: NGF-stimulated transcription
Gene Ontology:
Molecular function: protein binding; transcription regulator inhibitor activity; transcription corepressor activity; protein dimerization activity; RNA polymerase II-specific DNA-binding transcription factor binding
Biological process: negative regulation of DNA-templated transcription; negative regulation of transcription by RNA polymerase II; neuron differentiation; circadian rhythm
Cellular component: nucleoplasm; nucleus; cytoplasm
Genetic constraint (gnomAD): Loss-of-function variants: 9 observed, 5.82 expected, observed/expected ratio (o/e) 1.55, 90% interval 0.88 to 1.94. That is too few expected variants to judge how well the gene tolerates losing a copy. Missense variants: 270 observed, 187.74 expected, observed/expected ratio (o/e) 1.44, 90% interval 1.3 to 1.59. Synonymous variants: 180 observed, 102.58 expected, observed/expected ratio (o/e) 1.75, 90% interval 1.55 to 1.94.
Homologues: Orthologues: chimpanzee ID4 (100% identical), macaque ID4 (100% identical), pig ID4 (100% identical), dog ID4 (99% identical), mouse Id4 (98% identical), rat Id4 (91% identical), tropical clawed frog id4 (55% identical), zebrafish id4 (52% identical), Drosophila melanogaster emc (29% identical). Paralogues in human: ID2 (42% identical), ID1 (40% identical), ID3 (34% identical).
Diseases named in the same sentence as ID4 in open-access papers:
ID4 is named in the same sentence as 115 diseases in open-access papers, as found by Europe PMC text mining. Sharing a sentence is not in itself a finding about the gene and the disease. The quoted sentences say what the papers report.
breast cancer (60 papers, 2005 to 2025). A primary or metastatic malignant neoplasm involving the breast. "ID4 expression and prognostic power are associated almost exclusively with basal-like breast cancer." (PMID 38321003, 2024). "The association between ID4 expression and overall survival of breast cancer patients was analyzed using the Kaplan–Meier plotter in GEPIA2." (PMID 38188675, 2023). "The anti-differentiation role of ID4 allowed its participation in the evolution of aggressive basal-like breast cancers that are associated with advanced disease and unfavourable patients' prognoses." (PMID 36510219, 2022). "The gene mapping of 24 DEGs through PubMed, OMIM, MeSH, and PMC databases provided eight significant breast cancer associated genes: ID4, NCOA1, RHEB, PDZK1, PLAUR, AKC1R2, ANXA1 and SLIPI." (PMID 33593445, 2021). "ID4 overexpression induced phenotypic changes associated with a tumor suppressor role for this protein in ER+ breast cancer cell lines." (PMID 30139383, 2018). "ID4, a member of the ID (inhibitors of differentiation) family of proteins, is associated with a stem-like phenotype and poor prognosis in basal-like breast cancer." (PMID 29921315, 2018). "Another gene, ID4, has also been identified as a breast-cancer-associated gene, which participates in the regulation of basic helix-loop-helix transcription factors." (PMID 29534550, 2018). "Beger and colleagues showed that an increase in ID4 expression was associated with the ability of breast cancer cells to exhibit anchorage-independent growth, while its depletion determined their morphological change to large and flat epithelial phenotypes." (PMID 24475217, 2014). "We found a tight correlation (P<0.0001) between ID4 promoter methylation and loss of ID4 expression in primary breast cancer 3 specimens." (PMID 18513385, 2008). "Methylation of ID4 correlated with increased risk of lymph node metastasis in T1 stage breast cancer, and histopathological tumor grade and poorer prognosis in colorectal carcinoma." (PMID 18831746, 2008). "We found an increased risk for tumour recurrence in breast cancer patients with ID4 promoter methylation (P = 0.036) compared to patients with lack of ID4 methylation." (PMID 18513385, 2008). "Demethylating treatment with breast cancer cell lines was associated with clear ID4 mRNA re-expression." (PMID 18513385, 2008). "Our next aim was to demonstrate for the first time a correlation between ID4 promoter methylation and loss of ID4 mRNA and protein expression in primary human breast cancer specimens." (PMID 18513385, 2008). "Compared to a normal breast tissue standard (12 pooled normal breast tissues) loss of ID4 mRNA expression in unmethylated breast cancer specimens was marginal (median fold change = 1.3)." (PMID 18513385, 2008). "In contrast, methylated breast cancer specimens exhibited a highly significant (P < 0.001) loss of ID4 expression (median fold change = 12.3)." (PMID 18513385, 2008). "In the context of breast cancer, high ID4 expression is associated with triple-negative breast cancer (TNBC) and basal-like breast cancer (BLBC) subtypes, where the ID4 gene might be amplified/overexpressed, and marks a subset of cancers with poor prognosis." (PMID 32054109, 2020). "Further resolving the function of ID4 in BLBC will require detailed biochemical analysis of DNA repair functional assays, genetic studies with ID4 knockout cells or animals and access to a large cohort of familial breast cancers with detailed gene copy number, BRCA1 mutation and methylation data." (PMID 32527287, 2020).
breast cancer (continued). "We therefore assessed whether there is evidence for copy number change of ID4 in (i) sporadic disease or (ii) in the context of familial breast cancer driven by germline BRCA1 mutation." (PMID 32527287, 2020). "In addition, ID4 was associated with mammary carcinoma drug resistance however its functions and contributions remain insufficiently defined." (PMID 32328189, 2020). "In the present study, we investigated whether ID4 protein exerts its pro-angiogenic function while also modulating the activity of tumour-associated macrophages in breast cancer." (PMID 29921315, 2018). "Moreover, increased ID4 expression has been associated with the ability of breast cancer cells to exhibit anchorage-independent growth." (PMID 30139383, 2018). "Our results demonstrate a highly significant loss of ID4 mRNA in 83% of human breast cancers." (PMID 18513385, 2008). "In order to demonstrate that ID4 promoter methylation may be associated with ID4 gene silencing, we performed demethylation analyses with four human breast cancer cell lines (MDA-MB231, BT20, MCF7 and T47D)." (PMID 18513385, 2008). "ID4 promoter methylation is indeed associated with ID4 gene silencing in human breast cancer cell lines as in vitro demethylation experiments with DAC in three methylated breast cancer cell lines restored abundant ID4 mRNA expression." (PMID 18513385, 2008). "Methylation of ID4 has been reported in and associated with the silencing of gene transcription and loss of protein expression in lymphoma, and gastric, colorectal and breast carcinoma." (PMID 18831746, 2008). "In addition, ID4, another factor highly induced by the ERβ variants has been shown to control mammary stem cells and mark breast cancers with a stem cell like phenotype and when expressed in prostate cancer is associated with increased risk for distant metastases." (PMID 30555629, 2018). "Taken together, our results reveal that ID4 protein, previously shown to control the stem-like phenotype of normal and transformed mammary epithelial cells, also controls the angiogenic potential in breast cancer through the modulation of tumor-associated macrophage activity." (PMID 29921315, 2018). "ID4 is overexpressed in a subset of breast cancer patients, marking patients with poor survival outcomes." (PMID 38332687, 2024). "Here, we performed GSEA to identify the most correlated pathways to ID4 expression in the TCGA breast cancer dataset using gene sets of the Molecular Signature Database (MSigDB)." (PMID 38321003, 2024). "Correlation analysis of ELK3 and ID4 expression in breast cancer cells was performed using breast cancer cell line microarrays from GEO (accession code GSE41313)." (PMID 38188675, 2023). "Kaplan–Meier plots also indicated that breast cancer patients with low ID4 expression had significantly poorer overall survival than patients with high ID4 expression (high ID4, n = 639; low ID4, n = 427; analyzed by GEPIA2)." (PMID 38188675, 2023). "Our group recently demonstrated that ID4 expression in breast cancer cells drives TAM reprogramming by increasing the expression of two pro-angiogenic factors, granulin (GRN) and HIF." (PMID 35202089, 2022).
breast cancer (continued). "One report showed that in vitro inhibition of ID4 expression in MCF-7 breast cancer cells following magnetothermal therapy (MTT) using specialized nanoparticles produced a potent reduction in cell viability." (PMID 36510219, 2022). "In breast cancer, miR-1908-3p promotes the invasion and metastasis of breast cancer MCF-7 cells by targeting eight genes including ID4, thereby promoting the progression of breast cancer." (PMID 35463352, 2022). "miR-1908-3p targets 8 genes including ID4 and promotes the proliferation, invasion, and metastasis of breast cancer cells (MCF-7)." (PMID 35463352, 2022). "Of note, ID4 was reported to be engaged in the pathogenesis and progression of breast cancer particularly basal-like breast cancer that enriches in stem cells population providing inferior prognosis." (PMID 36510219, 2022). "High ID4 expression is indeed associated to TNBC and, specifically, to those TNBC with basal phenotype, namely basal-like breast cancer (BLBC), where ID4 marks a subset of poor prognosis cancers." (PMID 35710947, 2022). "In breast cancer biopsies, ID4 and ID1 are overexpressed in a subset of samples that predominantly presented more aggressive phenotypes and shorter overall and disease-free survival." (PMID 33514024, 2021). "We confirmed that the overexpression of ID1 and ID4 correlated with more aggressive phenotypes and poor survival in breast cancer patients’ samples." (PMID 33514024, 2021). "The oncogenic role of ID4 has also been reported in lung cancer, hepatocellular carcinoma, and breast cancer." (PMID 34903206, 2021). "ID4, which is the ID family member that differs the most in terms of sequence and function, is highly expressed in breast cancer cell lines than breast healthy tissue cell line." (PMID 33514024, 2021). "In this study, we report that the expression levels of ID4 appeared to correlate with breast cancers subtype differentiation biomarkers (including ER, PR) and chemo-resistance related proteins (including MRP1, ABCG2, P-gp)." (PMID 32328189, 2020). "Inhibitor of DNA binding factor 4 (ID4) was reported to play diverse roles in different breast cancer molecular phenotypes." (PMID 32328189, 2020). "To further investigate the function of ID4 in breast cancer chemo-resistance, we performed conventional CCK8 assays to identify the sensitivity of Adriamycin in breast cancer cells." (PMID 32328189, 2020). "To further investigate the potential function of ID4 in chemo-resistance, we analyze the TCGA database and found that the expression of ID4 correlated with the Notch1 pathway in breast cancer." (PMID 32328189, 2020). "On the contrary, PBDM cultured with conditioned medium (CM) derived from ID4-overexpressing breast cancer cells (ID4-HA) showed a much stronger and time-dependent ID4 mRNA induction compared to the control CM (empty vector, EV)." (PMID 32054109, 2020). "The potential target genes of miR-1908-3p in breast cancer included ID4, LTBP4, GPM6B, RGMA, EFCAB1, ALX4, OSR1 and PPARA." (PMID 32650755, 2020). "According to Kaplan–Meier plotter, low expression of CD109, ID4, NR4A1, and SYCP3 is associated with poor RFS in breast cancer patients." (PMID 32679794, 2020). "In this study, we demonstrated that ID4 regulates the drug resistance of breast cancer by connecting with Notch1 in a new way." (PMID 32328189, 2020). "In this study, starting from the observation that breast cancer cells induce the expression of ID4 in neighboring macrophages, we explored the mechanisms of ID4 activation and the functional involvement of ID4 in TAM activity." (PMID 32054109, 2020).
breast cancer (continued). "In an effort to discover novel ID4 functions in this study, we firstly detected the expression of ID4 in 100 breast cancer tissues after surgery and analyzed the correlation between the ID4 and breast cancer phenotype markers and some ABC transporters." (PMID 32328189, 2020). "We first detected the expression of ID4, ER, PR and Her-2 in 100 breast cancer tissues via immunochemistry." (PMID 32328189, 2020). "In order to further explore the regulatory mechanism of ID4 on MRP1, we used TCGA to analyze the main downstream signaling pathways of ID4 in breast cancer and found that Notch1 pathway has been involved in many development processes." (PMID 32328189, 2020). "Firstly, we found that the expression of ID4 was associated with chemo-resistant ABC transporter proteins, including MRP1, ABCG2, P-gp in breast cancer resection samples." (PMID 32328189, 2020). "The expression of ID4 also negatively correlated with ER and PR expression in 54 breast cancer cell lines according to the TCGA database." (PMID 32328189, 2020). "In basal-like breast cancers on the other hand, ID4 is overexpressed and related with poor prognosis and a stem-like transcriptional profile." (PMID 32328189, 2020). "Considering the in vitro involvement of ID4 in breast cancer cell proliferation and chemo-resistance, we extended this study to determine the impact of ID4 on tumorigenic capabilities of breast cancer cells in vivo." (PMID 32328189, 2020). "Using the TCGA data base, we found that ID4 expression was negatively correlated with the ER, PR in 1214 breast cancer tissue samples." (PMID 32328189, 2020). "Together, these results demonstrate that breast cancer cells determine a paracrine induction of ID4 expression in macrophages." (PMID 32054109, 2020). "Among significantly downregulated genes with promoter hypermethylation, CDON, ID4, and CPEB1 were associated with neuroblastoma, breast cancers, and hepatocellular carcinoma, respectively." (PMID 31796082, 2019). "Increased ID4 expression has been informed in basal cell-like breast cancer, and we found increased expression and hypomethylation of its promoter in triple-negative breast cancer (TNBC)." (PMID 30139383, 2018). "To test this, we used the singular-value decomposition (SVD) analysis and studied the expression of ID4 vs. the expression of 66 genes with different functions in breast cancer in 780 samples from TCGA database." (PMID 30139383, 2018). "At the molecular level, ID4 protein expression in breast cancer cells controls, through paracrine signalling, the activation of an angiogenic programme in macrophages." (PMID 29921315, 2018). "Next, we used cell migration assays to evaluate the effect of ID4 expression modulation in breast cancer cells on the motility of co-cultured macrophages." (PMID 29921315, 2018). "We propose that ID4 is frequently silenced by promoter methylation in ER+ breast cancers and functions as a tumor suppressor gene in these tumors, probably due to its interaction with key genes of the ER pathway." (PMID 30139383, 2018). "Based on our in silico conclusions, we decided to extend our studies and measure tumoral behavior by modulating the expression of ID4 in cultured ER+ breast cancer cell lines." (PMID 30139383, 2018). "In vitro and in vivo migration assays demonstrated that expression of ID4 in breast cancer cells stimulates macrophage motility." (PMID 29921315, 2018). "A study also revealed that ID4 and BRCA1 expression are inversely related and unmethylation of ID4 is associated with BRCAness of breast cancer cells." (PMID 29298879, 2018). "The relationship between ID4 expression and OS of 799 breast cancer patients was analyzed separating ER+ (n = 548) from ER− (n = 251) cases." (PMID 30139383, 2018). "We propose that ID4 is frequently silenced by promoter methylation in ER+ breast cancers and functions as a tumor suppressor gene in these tumors, probably because of its negative interaction with key genes of the ER pathway." (PMID 30139383, 2018).